NRP1 (neuropilin 1)
Diseases named in the same sentence as NRP1 in open-access papers (continued):
Sharing a sentence is not in itself a finding about the gene and the disease.
tumor (continued). "In addition, for the validation cohort, there was decreased risk of cancer‐related death with NRP1 expression in tumor cells (HR = 0.3, 95% CI = 0.2–0.5, p‐value <0.001) and perivascular NRP1 (HR = 0.3, 95% CI = 0.2–0.4, p‐value <0.001)." (PMID 31880322, 2020). "In summary, based on our systematic analyses of NRPs and PLXNs in terms of their expression, association with patient survival, immune subtype, and tumor infiltration, we found that NRP1, NRP2, PLXNA1, PLXNA3, PLXNB3, PLXNC1, PLXND1 were mainly associated with poor prognosis." (PMID 32640719, 2020). "Moreover, we observed a significantly higher percentage of tumor-associated antigen-specific CD8+ T cells in tumors producing anti-NRP-1 Nbs." (PMID 33266104, 2020). "As we found that NRP‐1 expression was associated with GBC tumour differentiation, targeting NRP‐1 might also be used for the GBC grading diagnosis." (PMID 32951327, 2020). "Notably, using a co-transfer model of NRP1-intact and NRP1-deficient Tregs, interferon (IFN)-γ produced by NRP1-deficient Tregs is capable of causing fragility to the suppressive capacity of NRP1-intact Tregs, resulting in improved host anti-tumor immunity." (PMID 32849557, 2020). "The contradictory prognostic value of NRP1 expression among types of cancers might be caused by the tumor-specific roles of NRP1 and its related mechanisms." (PMID 32408477, 2020). "In addition, recently both Gal-1 and NRP1 have been independently implicated in cancer immune escape and as putative targets for tumor immunotherapy, potentially featuring a pathway that deserves further investigation." (PMID 32784465, 2020). "For example, high NRP1 expression and hypermethylation were associated with poor GC prognosis, whereas another study indicated that it could be an anti-tumor target." (PMID 32849822, 2020). "NRP1 is also highly expressed in tumor-associated blood vessels." (PMID 31652529, 2019). "Although studies manipulating tumor-associated monocytes/macrophages show only small increases in M1-like cytokines and chemokines (such as TNFα, IL1β etc.), the greatest increase was seen following monocyte-specific NRP1 ablation." (PMID 30479695, 2018). "We sought to understand the epigenetic underpinnings between Nrp1-sufficient and -deficient Tregs from the tumor microenvironment that could lead to this ‘fragile’ state." (PMID 30400822, 2018). "Moreover, accumulating evidence has associated Nrp1 expression in cancer cells with tumor progression." (PMID 30360368, 2018). "NRP1, which is expressed in GAMs has been associated with tumor promotion." (PMID 29067024, 2017). "Nrp1 as a TGFβ receptor signaling component has been reported previously in fibroblasts, endothelial cells and immune cells, and has been implicated as a driver of tumor progression." (PMID 28938007, 2017). "Thus, our in vivo data were consistent with our in vitro data proposing that NRP1 deficiency in KRASmt cells was pro-tumorigenic but seems to inhibit tumor growth in KRASwt cells." (PMID 29018205, 2017). "Therefore, we were intrigued at literature reporting a potential interaction between B7x and NRP1, given the B7x associated rise in Tregs and M2 TAMs found in our tumor model." (PMID 29137299, 2017). "Nrp-1 impairment leads to the loss of Treg suppression and subsequent inhibition of tumor growth." (PMID 27075020, 2016). "These in vivo results suggest that loss of NRP-1 could potentially lead to reduced tumor growth, angiogenesis and fibrosis possibly through limiting EndMT as well as reducing NRP-1-VEGFR-2 signaling." (PMID 27542226, 2016). "Inhibition of NRP-1 function may also result in modulation of signal transduction pathways triggered by growth factors other than VEGF-A, such as PDGF, FGF, EGF, and HGF, which are implicated in tumor progression and are capable of binding NRP-1." (PMID 26090340, 2015).
tumor (continued). "SEMA3A-induced tumor vessel normalization might be indirectly caused by SEMA3A-mediated recruitment of a subset of NRP1-expressing monocytes that secrete several factors involved in vessel maturation." (PMID 24521511, 2014). "A ten-fold increase in NRP1 density in the tumor causes uncomplexed NRP1 to dominate." (PMID 18713470, 2008). "Similarly, NRP-1 expressed in glioma TAMs has been associated with tumor promotion." (PMID 39857591, 2024). "Additionally, NRP1’s role as a co-receptor for TGF-β1 may facilitate processes linked to tumor progression, such as cell proliferation and metastasis." (PMID 39334861, 2024). "However, when Treg cells lack IL-33, the tumor microenvironment changes, causing the cells to transform into “fragile” Treg cells with considerably increased PD-1 expression, lower neuropilin-1 (Nrp-1) expression, and loss of IL-33’s inhibitory effect on NF-κB." (PMID 37686309, 2023). "In addition, murine Nrp1-deficient Tregs are associated with a profound tumor resistance due to Treg functional fragility with the acquisition of characteristic T-helper lineage markers (such as T-bet, CXCR3, IRF4 and RORγt), even if they retain their Foxp3 expression." (PMID 33924428, 2021). "Thus, it is likely that the NRP1 variants are secreted by exosomes and continuously internalize and sustain the active NRP1 variants/Met/β1-integrin complexes on endosomes, and thereby, provide persistent endosomal signals for tumor progression." (PMID 31420553, 2019). "NRP1 has a protumorigenic role and direct contribution to tumor progression in some studies where NRP1 is predominantly expressed in epithelial cancer cells, including carcinomas of lung, breast, prostate, pancreas and colon and is implicated in the survival, migration and invasion of tumor cells." (PMID 24926961, 2014). "Thus, Nrp1 is a specific marker of Tfh cells cognate activation in humans, which may prove useful as a prognostic factor and a therapeutic target in neoplastic diseases associated with Tfh cells activity." (PMID 24386482, 2013). "NRP1 is broadly expressed across tumor compartments, and stromal, particularly endothelial, NRP1 is a key mediator of iRGD activity, associated with poor prognosis, representing a potential therapeutic entry point." (PMID 42166776, 2026). "This review systematically explores the panoramic regulatory framework of the NRP1-autophagy axis in the tumor immune microenvironment through bidirectional regulation of activating immunity and inhibitory immunity at the pan-cancer level." (PMID 41948345, 2026). "Fusion of tLyP-1 to human ferritin nanospheres further augments cellular uptake and tumor penetration, while NRP-1 targeting in CD8+ T cells enhances PD-1 blockade efficacy and promotes long-term immune memory." (PMID 41590805, 2026). "Overall, our results support a role for NRP1 in mediating tumor cell growth stimulated by both PlGF and VEGF." (PMID 41306516, 2025). "Among the numerous tumor markers, NRP1 and GLUT1 have gained significant attention due to their close association with tumor occurrence and progression." (PMID 40048021, 2025). "The overexpression of NRP1 has been observed in numerous cancer types, correlating with poor prognosis and increased tumor aggressiveness." (PMID 40277760, 2025). "One of the principal mechanisms by which NRP-1 and -2 contribute to tumor biology is through the induction of angiogenesis." (PMID 40430075, 2025). "In this study, we showed that NRP1+ non-tumor cells identified in the TME of MB tissues correlate with CD68 expression, indicating high NRP1 expression in TAMs." (PMID 40805120, 2025). "Preclinical evidence indicates that inhibiting NRP1 not only suppresses tumor growth by impeding angiogenesis but also directly hinders tumor cell proliferation in specific models." (PMID 40343434, 2025).
tumor (continued). "NRP1 is now known to be a tumor promoter, and several studies have been conducted, but effective targeting of NRP1 as a potential therapeutic target has not been achieved to date." (PMID 40277760, 2025). "In fact, tumor cells recruit Treg cells via the Neuropilin1 (Nrp1)-VEGF axis to generate an immunosuppressive environment." (PMID 40977681, 2025). "Knockdown or depletion of EZH2 in tumor cells significantly enhanced the inhibitory effects of paclitaxel, docetaxel, and cisplatin on tumor cells, leading to a striking reduction in NRP1 levels." (PMID 40314246, 2025). "Beyond its role in axonal guidance and angiogenesis, NRP1 is increasingly recognized for its significant impact on tumor progression and therapeutic outcomes." (PMID 40277760, 2025). "Other work has identified specific peptides able to block NRP1 interactions with VEGF165 and induce apoptosis of NRP1-expressing tumor cells." (PMID 40277760, 2025). "Expression of Nrp-1 and/or Nrp-2 has been found in different cell types, such as endothelial cells, neurons, pancreatic islet cells, hepatocytes, and tumor cells." (PMID 40430075, 2025). "NRP-1 is a cell surface receptor that plays a multisystem role in angiogenesis, tumor progression, and axonal guidance by acting as a receptor for ligands such as vascular endothelial growth factor-A, integrins, and transforming growth factor-β." (PMID 40584180, 2025). "Our group has shown that NRP1 ablation of patient-derived GBM cells enhances the overall survival in tumor-bearing mice." (PMID 40277760, 2025). "iRGD initially binds to αβ integrins overexpressed on tumor cells and vasculature, then undergoes proteolytic cleavage to expose a CendR motif, which binds to Nrp1 and promotes tumor penetration and cellular uptake." (PMID 41471261, 2025). "Functional studies have demonstrated the potential role of the transmembrane-coreceptor, Neuropilin-1 (NRP1) in regulating the progression of these tumours." (PMID 41326436, 2025). "Tumor vasculature showed strong endothelial NRP1 expression, while perivascular astrocytic coverage was frequently absent." (PMID 40805120, 2025). "NRP1 silencing has been shown to impair the activity of these growth factors and inhibit tumor growth in some instances, although further investigations are required to verify this." (PMID 40277760, 2025). "Further, an increased NRP1 expression has been found to increase the vessel number and cause poor prognosis, while increased expression of NRP2 stimulates tumor progression, and down-regulation of NRP2 expression inhibits colon cancer tumorigenesis." (PMID 40277760, 2025). "In MB, the role of NRP1 has been investigated in both in vitro and in vivo models as well as in human tumor tissue." (PMID 40805120, 2025). "NRP1 has been extensively validated for its role in tumor drug resistance, particularly through the regulation of Yes-Associated Protein (YAP) and the PI3K/AKT signaling pathway." (PMID 40228435, 2025). "Studies from our lab show that the target of VEGF synthesis and the disruption of the VEGF/NRP1 axis is known to activate proangiogenic and protumorigenic signaling in endothelial cells and ccRCC tumor cells." (PMID 40277760, 2025). "Elevated NRP-1 expression in resistant tumors supports proangiogenic activity and is associated with enhanced EMT and activation of AKT and ERK pathways, promoting tumor progression." (PMID 40430075, 2025). "A7R dissociated from the micelle complex targets VEGFR-2 and NRP-1 on tumor endothelial cells to normalize blood vessels." (PMID 40235732, 2025). "Recent work has shown that DHODH sustains tumor macropinocytosis through O-GlcNAcylation of neuropilin-1 (NRP1), which promotes nutrient scavenging and suppresses MHC class II expression on tumor cells." (PMID 41369379, 2025). "Given these gaps in our current knowledge, a better understanding of NRP1 expression in the tumor microenvironment is needed." (PMID 40805120, 2025).
tumor (continued). "VEGF signaling activates NRP1 in CSCs, which enhances stemness and proliferative gene expression, sustaining tumor growth and CSC maintenance." (PMID 40399946, 2025). "Among them, the membrane-penetrating peptide tLyP-1 has been shown to specifically target binding to NRP-1 proteins that are highly expressed in tumors and also to penetrate tumor vasculature and stroma to reach deep into the tumor." (PMID 41306963, 2025). "A subsequent investigation into the comparison between the NRP isoforms for the expression levels between the SKCM cells of the TP and normal clusters highlights that NRP2 is notably increased in the presence of tumour compared to NRP1." (PMID 40134439, 2025). "NRP1, a transmembrane protein, promotes angiogenesis and tumor growth by interacting with TGF‐β signaling pathways." (PMID 39083441, 2025). "This drives tumor progression and resistance to irinotecan, with NRP1 knockdown partially reversing the effects of EZH2 overexpression on both cell proliferation and autophagy suppression." (PMID 40314246, 2025). "Functional studies demonstrated that NRP1 is a key effector mediating HIF-1α-induced tumor migration, invasion, and VM formation, and that targeting the HIF-1α-induced overexpression of NRP1 can inhibit the malignant progression of LUAD." (PMID 41019994, 2025). "In ovarian cancer, NRP-1-positive CAFs promote tumor growth and metastasis through interactions with tumor cells." (PMID 40094065, 2025). "To evaluate the probe's targeting efficacy towards NRP1 in vivo, we selected MDA-MB-231, HCT116, and NCI-H1299 tumor-bearing mouse models, each representing different levels of NRP1 and GLUT1 expression." (PMID 40048021, 2025). "Neuropilin-1-targeting peptides (CPL-K, CPL-F) interact with NRP-1, a receptor involved in tumor angiogenesis, to improve drug accumulation in tumor tissues." (PMID 40286158, 2025). "NRP1, a transmembrane protein present on the tumor surface, facilitates the entry of PROTACs into tumor cells, thereby enhancing permeability." (PMID 40143076, 2025). "The iRGD peptide enhances the drug permeability and accumulation in tumor tissues by binding to the overexpressed αv integrin and neuropilin-1 on tumor blood vessels and glioma cells." (PMID 40142943, 2025). "Studying its novel receptor, NRP1 has proven to be a likely therapeutic target for preventing metastasis and slowing tumor growth." (PMID 40277760, 2025). "The iRGD is a tumor-penetrating peptide that binds to αvβ3/αvβ5 integrins and is cleaved to expose a CendR motif, which interacts with neuropilin-1 (NRP-1) to enhance tissue penetration, including BBB crossing." (PMID 40533746, 2025). "NRP1 was detected on occasional tumor cells, but its expression was particularly evident in round cells with glial morphology located between tumor cells and in the endothelium." (PMID 40805120, 2025). "Therapeutically, targeting NRP1 holds promise as a novel strategy to inhibit tumor growth and enhance the efficacy of regular treatments such as chemotherapy and radiotherapy." (PMID 40277760, 2025). "To investigate the involvement of NRP1 at the BBB, we compared endothelial NRP1 staining with the presence of astrocytic end feet (GFAP+) surrounding or in close contact with tumor vessels." (PMID 40805120, 2025). "The internalizing RGD (iRGD) peptide is a dual-function tumor-penetrating peptide, interacting with αvβ3 integrins and neuropilin-1 (NRP-1)." (PMID 40286158, 2025). "It has been demonstrated that platelet-derived growth factor-B (PDGF-B) secreted from tumor cells promotes the differentiation of MSCs into pericytes via interaction with neuropilin-1." (PMID 40676710, 2025). "In conclusion, despite NRP-1′s complicated role in endothelium and cancer cells, as well as its participation in tumor growth, it remains a prospective therapeutic target for PDAC." (PMID 40430075, 2025).
tumor (continued). "Semaphorin 3 G acts as a key regulator of cancer immune responses by controlling the cytotoxicity of CD8+ T cells via NRP1, thereby suppressing tumor growth." (PMID 40228435, 2025). "Several approaches are being explored to disrupt NRP1 function and impede tumor growth: Antibody-Based Therapies: Monoclonal antibodies targeting NRP1 have been developed to block its interaction with VEGF and other ligands involved in angiogenesis." (PMID 40277760, 2025). "In conclusion, NRP1 represents a multifaceted target in cancer therapy, influencing angiogenesis, cell migration, invasion, and immune regulation within the tumor microenvironment." (PMID 40277760, 2025). "Further, it was also reported that hypoxia-mediated HIF-1alpha-dependent upregulation of NRP-1 is a critical molecular event involved in the vasculogenic mimicry and tumor formation." (PMID 41035776, 2025). "Upon proteolytic cleavage within the tumor microenvironment, iRGD reveals its CendR motif, which subsequently binds to and activates neuropilin-1 (NRP-1), initiating trans-tissue transport." (PMID 41295604, 2025). "It has been discovered that Mucin 1, a transmembrane glycoprotein, is associated with NRP1 and responsible for inducing VEGF signaling and angiogenesis in the tumor environment." (PMID 40277760, 2025). "NRP1 is expressed by endothelial cells and tumor cells as an isoform-specific receptor for VEGF, and the extracellular domain of NRP1 allows it to bind to VEGF and act as a co-receptor for VEGF, enhancing the binding affinity and bioactivity of VEGF." (PMID 40277760, 2025). "Next, we analyzed the density of NRP1+ cells in tumor tissue, which showed a relatively homogeneous distribution across MB molecular subgroups." (PMID 40805120, 2025). "Neuropilin-1 (NRP-1) is a glycoprotein critical in tumor progression, angiogenesis, metastasis, and cell proliferation." (PMID 40419692, 2025). "The present study introduces the novel concept of a dual-functional peptide-modified liposome (SAPSp-iRGD-lipo) that integrates the pH-responsive behavior of SAPSp with the NRP-1-mediated tumor-penetrating ability of iRGD." (PMID 41295604, 2025). "These approaches aim to disrupt the NRP1-mediated signaling pathways, inhibiting tumor growth and metastasis." (PMID 40277760, 2025). "TIM3, CD39, PD1, and NRP1 in CD8+ T cells were significantly elevated in peri-tumor tissues as compared to those in the peripheral blood PBMCs of NSCLC patients and further elevated in tumor tissues (P < 0.001)." (PMID 40040705, 2025). "NRP1 overexpression correlates with tumor aggressiveness, advanced disease stage, and poor prognosis." (PMID 40277760, 2025). "This study seeks to develop a novel near-infrared fluorescence (NIRF) probe aimed at precise tumor detection by targeting NRP1 and GLUT1." (PMID 40048021, 2025). "Sema3A is produced in cancer cells and dysfunctional tumor-specific CD8+ T cells and can modulate anti-tumor response by upregulating NRP1, such as PD-1." (PMID 40277760, 2025). "We showed that BA inhibits the growth of tumour cells by inducing the SEMA3A/PLXNA1/NRP1 pathway and prevents cell growth by inducing oxidative damage and activating apoptosis through excessive ROS generation." (PMID 40318008, 2025). "It was concluded that the tumor-penetrating peptide utilizes the NRP-1-regulated transcytosis transport pathway." (PMID 40430075, 2025). "The co-enrichment of CTSL and CTSB, in conjunction with elevated NRP1 levels, contributes significantly to angiogenesis and tumor invasion, marking the progression from a healthy state to the development of ccRCC." (PMID 40134439, 2025). "Patient-derived GBM cells express shRNA of VEGF or NRP1 attenuate cancer stem cells (CSCs), inhibiting the tumor-initiating cell’s neurosphere forming capacity and migration." (PMID 40277760, 2025). "In MB, NRP1 promotes tumor cell survival and supports the maintenance of cancer stem cells, metastasis and angiogenesis." (PMID 40805120, 2025).